TNF (tumor necrosis factor)
Diseases named in the same sentence as TNF in open-access papers (continued):
Sharing a sentence is not in itself a finding about the gene and the disease.
Insulin resistance (continued). "It is well known that tumor necrosis factor-α (TNF-α) is responsible for causing insulin resistance, but the administration of pioglitazone has shown to reduce the expression of TNF-α." (PMID 33308138, 2020). "Specifically, pro-inflammatory cytokines like TNFα, which are secreted as a result of the interaction between adipocytes and macrophages have been linked to dysfunctions in glucose metabolism and insulin resistance." (PMID 32418005, 2020). "In the pathogenesis of T2DM, increased production of TNF-α in adipose tissues is also related to the obesity-associated insulin resistance that leads to the development of T2DM." (PMID 32148647, 2020). "TNF-α is among the first proinflammatory biomarkers to be associated with the pathogenesis of insulin resistance and glucose-related abnormalities that link to T2DM." (PMID 32148647, 2020). "Their study showed that TNFα was associated with inflammation and insulin resistance in both Japanese older men and women; a prominent association was observed between TNFα and malnutrition status in older women." (PMID 32297262, 2020). "In particular, proinflammatory cytokines, namely tumor necrosis factor alpha (TNFα), are implicated in the development of neuronal insulin resistance." (PMID 31991770, 2020). "TNF-α is associated with low-grade inflammation, possibly leading to insulin resistance and diabetes and contributes to the pathogenesis of atherosclerosis." (PMID 32708379, 2020). "Further, mice deficient in TNF and TNF receptor 1 & 2 were protected from diet-induced insulin resistance." (PMID 33178196, 2020). "When released by adipose tissue as adipokines, tumour necrosis factor-α (TNF-α) and interleukin-6 (IL-6) promote low-grade systemic inflammation, which in turn is associated with chronic deleterious conditions such as insulin resistance, T2DM and obesity." (PMID 33028418, 2020). "The secreted cytokines TNFα and IL-6 cause insulin resistance in adipocytes through IKKβ and JNK1 kinase pathway activation, which interfere with insulin signaling via phosphorylation and subsequent IRS1 inactivation." (PMID 32878255, 2020). "Pro-inflammatory cytokines such as IL-6 and TNF-α are implicated to promote insulin resistance by interfering with the insulin signaling pathway, leading to the pre-clinical manifestation of T2DM." (PMID 32694996, 2020). "At the beginning of the 21st century, the increased secretion of cytokines, especially TNF-α and IL-6, which contribute to insulin resistance, was proved to be linked to infiltration and accumulation of macrophages in adipose tissue." (PMID 32947869, 2020). "TNF-α secretion from adipose tissue has been associated with insulin resistance that impairs glucose uptake, decreased fatty acid oxidation, increased adipose tissue mass." (PMID 32819381, 2020). "His exhibited a protective effect on glucose, insulin, insulin resistance, lipid profile, cardiac risk ratios, renal functional markers, oxidative stress, and TNF-α." (PMID 32695286, 2020). "The adipocytokine signaling pathway includes the signaling cascades caused by adipocytokines (TNF-α, leptin and adiponectin), which are pivotal signaling molecules associated with insulin resistance." (PMID 32655508, 2020). "An increase in TNF expression causes subsequent cognitive decline and long-term cognitive impairment also causes insulin resistance and diabetes." (PMID 33585009, 2020). "Both type 1 and type 2 diabetic conditions are associated with significantly elevated levels of serum TNF-α and exhibit a positive correlation with insulin resistance." (PMID 32806520, 2020). "In adipose tissue, IL-6 and TNF-α were the activators of the NF-κB pathway, linked to insulin resistance in obesity." (PMID 33060792, 2020). "Neutrophils release TNF-α and IL-6 which cause insulin resistance directly via serine phosphorylation of IRS-1." (PMID 33208757, 2020).
Insulin resistance (continued). "As described in detail previously, the enlarging adipose tissue in obese subjects synthesizes and secretes hormones and proteins like leptin, adiponectin and TNF-α, which modify insulin secretion and sensitivity, causing insulin resistance." (PMID 32947869, 2020). "It was also found that “Inactive & Sedentary LS”, high BF%, insulin resistance, and ultra-sensitive C-reactive protein were associated with the concentrations of proinflammatory biomarkers of tumor necrosis factor-α, interleukin-6, and leptin." (PMID 32694929, 2020). "TNF-α is a critical proinflammatory cytokine associated with metabolic inflammation and insulin resistance." (PMID 32751118, 2020). "In this way, elevated IL-6 and TNF-α serum levels can lead to insulin resistance and the occurrence of loss of muscle mass and function." (PMID 32399298, 2020). "Recent experimental evidence has shown an increased inflammatory potential of adipose tissue in aged animals by overproduction of interleukin 6 (IL-6), IL-8, IL-1β, and tumor necrosis factor α (TNF-α) causing insulin resistance." (PMID 31900232, 2020). "In this study, serum resistin, leptin, and TNF-α levels were dramatically decreased by Pt-PS supplementation, which was associated with the alleviation of insulin resistance." (PMID 32971772, 2020). "For example, monoclonal antibody infliximab, which neutralizes TNF-α, is a new approach aimed at inflammation-associated insulin resistance." (PMID 31803062, 2019). "Inflammation in NAFLD is one of the main causes of insulin resistance with inflammatory markers such as TNF-α and IL-6 suppressing insulin receptor signaling, thus blocking the action of insulin in hepatocytes." (PMID 30764536, 2019). "It was reported that increased inflammatory cytokine levels such as TNFα and plasma hyperhomocysteinemia were associated with insulin resistance and endocrine abnormalities." (PMID 31200713, 2019). "In humans, the circulating concentration of TNF-α are elevated in T2D, and this alteration is strongly associated with impaired glucose tolerance and enhanced insulin resistance, islet dysfunction, and increased T2D risk." (PMID 31736870, 2019). "Adipose tissue inflammation which can be described by the NF-κB activation and inflammatory cytokines such as TNF-α upregulation is strongly associated with glucose intolerance, insulin resistance and type 2 diabetes." (PMID 31048563, 2019). "For example, IL-1, IL-6, and TNF-alpha that are linked to periodontal disease progression, are associated to insulin resistance too." (PMID 31835888, 2019). "The increased expression of TNF-α in the adipose tissue associated with adiposity and insulin resistance." (PMID 31718015, 2019). "Multiple systemic factors associated with insulin resistance, for example, free fatty acids and TNF-α, can reduce IRS-1 serine phosphorylation and thus inhibits its function." (PMID 30863203, 2019). "The activation of AMPK, SIRT1, FOXO3a and NF-κB signaling by TNF-α has been reported to cause inflammation and insulin resistance in several cell lines." (PMID 31100089, 2019). "Specifically, an increased density of the IL10 and TNFα-secreting CD11C+CD206+ ATMs in adipose tissue was associated with insulin resistance, which coincides with the observed increase of M-IL10 and M-LPSearly signals while the M-IL4 signal remained unaltered." (PMID 31921150, 2019). "Obesity-associated insulin resistance is accompanied by elevated levels of pro-inflammatory cytokines, such as TNF-alpha, IL-6, and IL-1-beta." (PMID 30881343, 2019). "The underlying mechanism of TNF-α-induced insulin resistance has been reported to mediate through the inflammatory signaling pathway including the activation of three MAPKs, p38, JNK1/2, and ERK1/2." (PMID 29955954, 2019). "Amongst others, adipose tissue releases inflammatory cytokines such as TNFα, which is associated with increased insulin resistance and increased lipolysis." (PMID 31466350, 2019).
Insulin resistance (continued). "Studies have shown that insulin resistance is associated with elevated plasma levels of TNF-α and causes a higher level of expression in tissues such as adipose and skeletal muscle." (PMID 30863203, 2019). "It was demonstrated that EFAD suppresses lipid accumulation and improves insulin resistance (IR) caused by Tumor necrosis factor alpha (TNF-α) in in-vitro experiments using the 3T3-L1 cell." (PMID 31212845, 2019). "High levels of pro-inflammatory cytokines such as TNF-α are also linked with insulin resistance and T2DM." (PMID 31569751, 2019). "The aim of this study is to investigate the effects of enzymatic egg white hydrolysate (EWH) and its responsible peptide, IRW, on TNF-α-induced insulin resistance and the underlying molecular mechanisms using rat skeletal muscle cells (L6 cells)." (PMID 29955954, 2019). "Tumor necrosis factor-α (TNF-α) is involved in insulin resistance and has long been a candidate gene implicated in type 2 diabetes mellitus (T2DM), however the association between TNF-α polymorphisms -308G/A and -238G/A and T2DM remains controversial." (PMID 31803921, 2019). "Adipose tissue-derived pro-inflammatory cytokines such as TNF-α and IL-6 can cause insulin resistance in adipose tissue, liver, and skeletal muscle by impairing insulin action." (PMID 31075962, 2019). "Multiple linear regression analysis showed that values of the adiponectin /TNF-α ratio were independently associated with insulin resistance." (PMID 29387323, 2018). "We have shown here that increased GM1 levels in aged and senescent ECs contribute to vascular insulin resistance caused by reduced eNOS levels even upon exposure to low concentrations of TNFα." (PMID 29464018, 2018). "High levels of both IL-6 and TNF-α have been reported to be associated with insulin resistance in the adipocytes, hepatocytes and myocytes." (PMID 30914847, 2018). "The phosphorylation of IRS-1 on serine residues is associated with insulin resistance induced by cytokines such as TNF-α, since it inhibits IRS-1 tyrosine phosphorylation leading to impaired insulin signaling." (PMID 29463262, 2018). "Prospective studies have shown that GDM is linked to the down-regulation of anti-inflammatory cytokines (e.g., IL-4 and IL-10) and up-regulation of pro-inflammatory cytokines implicated in insulin resistance (e.g., IL-6 and TNF-α)." (PMID 30563117, 2018). "Systemic inflammation has been considered a potential mediator of this association, with some cytokines, such as TNF-α, potentially involved in the regulation of systemic insulin-resistance." (PMID 30077530, 2018). "Pro-inflammatory cytokines such as IL-6 and TNF-α up-regulate the expression of the suppressor of cytokine signaling 3 (SOCS3) implicated in inflammation-mediated insulin resistance in the liver and adipocytes." (PMID 30360409, 2018). "Inflammatory mediators also have a causative effect in insulin resistance, with TNF-α being found to increase phosphorylation of insulin receptor substrate-1, which leads to diminished insulin signaling." (PMID 30249283, 2018). "TNF-α, a pro-inflammatory cytokine that is associated with insulin resistance, has been shown to inhibit adiponectin production, and the inhibition of TNF-α can improve glucose homeostasis and increase the serum levels of high-molecular-weight adiponectin." (PMID 29587377, 2018). "Chronic inflammation, such as elevated TNF‐α concentrations, is implicated in the development of peripheral insulin resistance." (PMID 30156033, 2018). "In presence of TNF-alpha the expression of sortilin is drastically decreased and can be associated with insulin resistance; on the opposite dexamethasone dependent insulin resistance is not accompanied by sortilin downregulation." (PMID 30697159, 2018). "The proinflammatory cytokine tumor necrosis factor alpha (TNFα) has been implicated in several metabolic disorders, including fatty liver disease and insulin resistance in dairy cattle." (PMID 29344353, 2018).
Insulin resistance (continued). "Chronic systemic inflammation, including elevated circulating cytokines such as TNF-α, has been previously associated with insulin resistance and hypercholesterolemia in mammals." (PMID 29304133, 2018). "These infiltrating macrophages cause the secretion of various inflammatory cytokines such as nitric oxide (NO) and tumor necrosis factor (TNF)-α, which can cause insulin resistance." (PMID 29329333, 2018). "Adipose tissue has been reported to produce pro-inflammatory cytokines, particularly TNF-α, which can impair insulin signaling, thereby increasing the risk of insulin resistance." (PMID 30249283, 2018). "Pregnancy is also associated with a transient worsening of the cardiovascular risk profile including increases in dyslipidaemia, insulin resistance, oxidative stress, cytokines such as IL-6 and TNF-α, and inflammatory markers such as CRP." (PMID 28193219, 2017). "TNF-α is a pro-inflammatory cytokine, which has also been implicated as a mediator in induction of insulin resistance and adipose tissue inflammation." (PMID 28348560, 2017). "This implies that high plasma levels of TNF-α and IL-6 seen in instances of insulin resistance is due to EPA, DHA, and AA deficiency." (PMID 28824543, 2017). "Of the major cytokines expressed in adipose tissue from obese subjects IL-1β, IL-6, and TNFα, have been linked with the development of insulin resistance." (PMID 28957383, 2017). "Tumor necrosis factor (TNF) is associated with insulin resistance and inflammation, which are characteristics found in Type II diabetes and can be a contributing factor that can lead to the pathogenesis of AD." (PMID 28553317, 2017). "For example, TNFα, can cause peripheral and hepatic insulin resistance; accordingly, upregulation of TNFα and IL-6 by chronic alcohol was associated with impaired insulin-mediated glucose uptake by WAT." (PMID 28212318, 2017). "Insulin resistance in skeletal muscle of 12 w HFD Trail−/− mice was associated with significantly increased expression of TNF-α." (PMID 28507343, 2017). "In obese adipose tissue, macrophages secrete inflammatory molecules such as TNFα and IL-1β which are linked to the development of insulin resistance." (PMID 28765650, 2017). "ATM1s produce large amounts of pro-inflammatory mediators such as TNF-α, IL-1β, and IL-6, which can cause insulin resistance in adipose tissue." (PMID 29141038, 2017). "Increased TNF-α concentrations from adipose tissue are typically observed in obese individuals, and are associated with insulin resistance." (PMID 28704429, 2017). "TNF-α and IL-6 can cause insulin resistance by suppressing expression of the insulin receptor substrate −1 (IRS-1) and GLUT-4 though activation of NF-KB pathway." (PMID 28166749, 2017). "Both cell culture and animal studies have shown TNF-alpha to interfere with the insulin pathway causing insulin resistance." (PMID 29209160, 2017). "Nevertheless, different reports coexist concerning the role of TNF-α in the cause of insulin resistance at the molecular level, which arises from actual cases where TNF-α in the blood was blocked." (PMID 28168013, 2017). "ER stress triggered by TNF-α has also been linked to peripheral insulin resistance in obesity and diabetes." (PMID 28197094, 2017). "TNF-α was a pro-inflammatory cytokine to be associated with insulin resistance due to reduced tyrosine kinase activity." (PMID 28166749, 2017). "TNF-α is involved in lipid metabolism, coagulation, insulin resistance, and endothelial function, while TNF-α 1031 allele C was associated with CHD risk and increased dyslipidemia." (PMID 28576445, 2017). "TNF-α is a major proinflammatory cytokine implicated in the metabolic syndrome, particularly insulin resistance." (PMID 28265178, 2017). "Adiponectin is a sensor of insulin and can induce body weight loss and insulin resistance, with high levels of tumor necrosis factor (TNF) in plasma and adipose tissue." (PMID 27547756, 2016).
Insulin resistance (continued). "Inflammation has been linked to insulin resistance and increased pro-inflammatory cytokines, such as TNF-α (tumor necrosis factor α), have been shown to cause insulin resistance in experimental models." (PMID 27070352, 2016). "Insulin resistance and hyperglycemia increase the effect of cytokines on the liver and cause the secretion of IL-6 and TNF-α from monocytes and macrophage." (PMID 28050278, 2016). "TNF-α has also been implicated as an insulin resistance-causing factor associated with the pathogenesis of T2DM." (PMID 27822481, 2016). "Chronic activation of these macrophages and their subsequent release of adipo-cytokines like TNF-α, IL-6, IL-1 and activation of NF-κB eventually cause insulin resistance in skeletal muscles." (PMID 27790148, 2016). "Insulin resistance in pregnancy has been particularly associated with adiponectin and leptin, which are secreted only by the adipose tissue, and IL-6 and TNF-α, which are also secreted by the adipose tissue and other cells." (PMID 27651836, 2016). "The data from the present study suggest a complex interaction of TNF-α, oxidative stress, and IR, but the presence of insulin resistance seems to be directly associated with both oxidative stress and TNF-α levels." (PMID 27340510, 2016). "We and others have shown that TNFα addition in cultures of primary human adipocytes causes insulin resistance." (PMID 26788115, 2016). "For instance, pro-inflammatory cytokines including interleukin (IL)-6 and tumor necrosis factor (TNF)-α enhance insulin resistance, and are associated with increased risk of type 2 diabetes." (PMID 27904436, 2016). "Increased production of pro-inflammatory cytokines such as TNFα and IL-6 has been reported to be associated with insulin resistance." (PMID 26913058, 2016). "Long-term treatment of adipocytes with IL-6, IL-1β, or TNFα was shown to inhibit insulin signaling and cause insulin resistance." (PMID 27066503, 2016). "S-adenosyl methionine (SAM) and betaine are nutritional supplements that have anti-TNF alpha, cytoprotective, antiapoptotic, and antisteatogenic activity and can cause reversal of insulin resistance." (PMID 27006654, 2016). "The presence of insulin resistance was robustly associated with both oxidative stress and TNF-α levels." (PMID 27340510, 2016). "Pro-inflammatory cytokines (such as tumor necrosis factor-α and interleukin-6) have been reported to be increased in depression and have also been implicated in the development of insulin resistance." (PMID 26891344, 2016). "Elevated levels of TNF-α in the liver are associated with the severity of diabetes, and IL-1β adversely affects the insulin signaling pathway and contributes to insulin resistance." (PMID 27929393, 2016). "TNF-α is a multifactorial regulatory cytokine, which has been implicated as mediator in induction of insulin resistance and adipose tissue inflammation." (PMID 25789857, 2015). "High levels of pro-inflammatory cytokines such as PAI-1, IL-6, TNF-α and reduced secretion of anti-inflammatory IL-10 are associated with increased insulin resistance." (PMID 26308010, 2015). "Various inflammatory cytokines, including IL-6 and TNF-α, have been shown to activate NF-κB to cause insulin resistance." (PMID 26843885, 2015). "Proinflammatory cytokines, such as IL-6 and TNF-α, are adipokines that have been associated with the development of insulin resistance and type 2 diabetes." (PMID 26170870, 2015). "Pro-inflammatory cytokines like IL-1β induces apoptosis in insulin-producing β-cells while CCL2 and TNFα are known to impair insulin signalling, and therefore causing insulin resistance." (PMID 27030821, 2015). "Insulin resistance is also an important risk factor for cardiovascular disease, as this results in increased secretion of proinflammatory cytokines, such as tumor necrosis factor-α and interleukin-6." (PMID 26618774, 2015).